PCDHB13 (protocadherin beta 13)
Description:
Potential calcium-dependent cell-adhesion protein. May be involved in the establishment and maintenance of specific neuronal connections in the brain.
Synonyms: PCDH-BETA13
Tractability: Antibody: UniProt places it where antibodies can reach, with medium confidence; UniProt predicts a signal peptide or a membrane-spanning region; its Gene Ontology location is reachable by antibodies, with medium confidence.
Gene: Protein-coding gene on chromosome 5 (141,213,919 to 141,218,979, forward strand). Ensembl gene ENSG00000187372.
Subcellular location: Cell membrane
Gene Ontology:
Molecular function: cell adhesion molecule binding; calcium ion binding
Biological process: calcium-dependent cell-cell adhesion; cell adhesion; chemical synaptic transmission; synapse assembly; homophilic cell-cell adhesion; nervous system development
Cellular component: membrane; plasma membrane; photoreceptor connecting cilium; photoreceptor disc membrane; postsynaptic membrane; synapse
Genetic constraint (gnomAD): Loss-of-function variants: 1 observed, 0.31 expected, observed/expected ratio (o/e) 3.27. That is too few expected variants to judge how well the gene tolerates losing a copy. Missense variants: 1,000 observed, 882.42 expected, observed/expected ratio (o/e) 1.13, 90% interval 1.08 to 1.19. Synonymous variants: 481 observed, 391.11 expected, observed/expected ratio (o/e) 1.23, 90% interval 1.14 to 1.33.
Homologues: Orthologues: macaque PCDHB13 (89% identical), rat AC131360.2 (76% identical), mouse Pcdhb16 (75% identical). Paralogues in human: PCDHB8 (92% identical), PCDHB16 (77% identical), PCDHB3 (75% identical), PCDHB15 (74% identical), PCDHB12 (74% identical), PCDHB14 (74% identical), PCDHB11 (74% identical), PCDHB2 (74% identical), PCDHB5 (74% identical), PCDHB10 (73% identical), PCDHB4 (73% identical), PCDHB6 (73% identical), and 49 more.
Diseases named in the same sentence as PCDHB13 in open-access papers:
PCDHB13 is named in the same sentence as 8 diseases in open-access papers, as found by Europe PMC text mining. Sharing a sentence is not in itself a finding about the gene and the disease. The quoted sentences say what the papers report.
non-small cell lung carcinoma (2 papers, 2019 to 2022). A group of at least three distinct histological types of lung cancer, including non-small cell squamous cell carcinoma, adenocarcinoma, and large cell carcinoma. "In concordance with our findings, PCDHB15 was identified as a part of a specific methylation signature across breast and colon cancer, as PCDHB13 in Non-Small Cell Lung Cancer." (PMID 36443814, 2022).
glioblastoma (1 paper, 2016). The most malignant astrocytic tumor (WHO grade IV). "Also, we used tool ‘GEO profiles’ of NCBI to search the expression of two homeobox genes (HOXA5 and HOXA10) and two cadherin genes (PCDHA1 and PCDHB13) in different grades of the glioblastoma." (PMID 27160082, 2016).
melanoma (1 paper, 2016). A malignant, usually aggressive tumor composed of atypical, neoplastic melanocytes. "With regard to the physiological importance of β-protocadherins, the only data in humans so far have revealed a very high expression of PCDHB11 and PCDHB13 on the melanoma cell surface." (PMID 27068704, 2016).
Obesity (1 paper, 2023). Accumulation of substantial excess body fat. "Twenty-one of these eGenes were detected only in GM and include genes with a role in diseases such as cancer (e.g. LUZP6 PCDHB13) and obesity (e.g. NTRK2), narrowing down the list of genes that constitute promising candidates for further study." (PMID 37543566, 2023).
tumor (1 paper, 2019). "To test whether protein expression correlates with mortality, we quantified the levels of FOSB and PCDHB13 in each tumor sample and normalized the values to the average from nine matched NAT samples." (PMID 30658436, 2019).
PCDHB13 also shares sentences with these, for which no sentence is quoted: cancer (1 paper); colon cancer (1); lung carcinoma (1).